ABCG2 (ATP binding cassette subfamily G member 2 (JR blood group))
Diseases named in the same sentence as ABCG2 in open-access papers (continued):
Sharing a sentence is not in itself a finding about the gene and the disease.
tumor (continued). "When expressed in tumor cells or tumor stem cells, ABCG2 confers multidrug resistance, contributing to the failure of chemotherapy." (PMID 36763413, 2023). "The expression of ABCG2 was down-regulated in HCC tissues when compared with paired non-tumor tissues, and knockdown of ABCG2 further prolonged the storage time of MHI-148 in HCC cells." (PMID 37064109, 2023). "After NE/E stimulation, the anaerobic glucolysis capabilities of tumor cells are enhanced to produce a large amount of ATP, which produces resistance to drug resistance through the action of ABCG2 and MRP1." (PMID 37489008, 2023). "No connection was noted between ABCG2 protein positivity and age, sex, tumour size or tumour shape, but higher TNM stage, poor differentiation and positive lymphovascular invasion were found to be associated with greater ABCG2 expression." (PMID 37445716, 2023). "Studies have shown that ABCG2 can transport a variety of anti-tumor drugs, such as epirubicin, daunorubicin, irinotecan, doxorubicin, topotecan, 9-aminocamptothecin and mitoxantrone." (PMID 37919637, 2023). "In recent studies, an increase in nitric oxide concentration was shown to mediate drug efflux inhibition by inactivating ATP binding cassette (ABC) transporters, such as ABCB1 (p-gp), ABCC1 (MRP1) and ABCG2 (BCRP) in tumor cells." (PMID 37228164, 2023). "We found that ABCC4 was significantly upregulated, whereas ABCG2 was downregulated in primary tumours in comparison to normal colon tissue." (PMID 38067326, 2023). "Lysergic acid (SDA) is known to downregulate tumor cell sphere-forming ability by regulating ABCG2 expression." (PMID 37674202, 2023). "ABCG2 is overexpressed in the side population of tumor stem cells, which play an important role in oral carcinogenesis." (PMID 36982894, 2023). "For example, it has been shown that the overexpression of ATP binding cassette transporter protein G2 (ABCG2) in tumor stem cells significantly enhance the natural ability to resist radiation, resulting in tumor radiotherapy tolerance." (PMID 37460952, 2023). "Bioinformatic analysis based on public transcriptome sequencing data from TCGA database indicated that ABCG2 was down-regulated in HCC tissues when compared with paired non-tumor tissues, which was also demonstrated in cell lines by Western Blotting." (PMID 37064109, 2023). "There are other transporters in the ABC superfamily, and a considerable amount of them contribute to tumor multidrug resistance, including the multidrug resistance proteins (MRPs/ABCCs) and breast cancer resistance protein (BCRP/ABCG2)." (PMID 36015347, 2022). "The enriched SP cells in several lung cancer cell lines (H460, H23, HTB-58, A549, H441, and H2170) showed high tumor-initiating properties, as well as elevated expression of the ABCG2 and ABC transporters that were insensitive to several chemotherapeutics." (PMID 35053430, 2022). "MRNAs encoding ABCG2 and ABCB1 were more abundant in CD44+CD133+ tumor-initiating Caco-2 cells than in ΔCD44+CD133+ non-tumor-initiating Caco-2 cells (i.e., the CD44−CD133- and CD44−CD133+ fractions)." (PMID 35433695, 2022). "Compared with paired non-tumor tissue, a significantly lower abundance of ABCG2 mRNA was determined in CRC biopsies obtained before the patients received antitumor therapy." (PMID 35884584, 2022). "The correlation between ABCG2 expression and tumor stemness measured by RNAss and DNAss was investigated." (PMID 36555598, 2022). "We then estimated chemotherapy-associated drug-resistant genes, including ABCB1, ABCC1 and ABCG2, and found that curcumol significantly reversed the mRNA levels of CDDP-induced ABCB1, ABCC1 and ABCG2 genes in the tumor tissue." (PMID 35889217, 2022). "In the current study, the levels of ABCG2 were downregulated in tumor tissues in local as well as TCGA cohort." (PMID 36309544, 2022).
tumor (continued). "ABCG2 the efflux pump determines the drug efflux capacity of the CSC sub-population phenotype and is associated with tumor progression, metastasis, and resistance." (PMID 35804016, 2022). "Distinct associations exist between ABCG2 expression and stemness scores, microenvironmental scores, microsatellite instability (MSI), and tumor mutational burden (TMB) of tumor patients." (PMID 36555598, 2022). "Previously, we characterized tumor stemness phenotype in the ATP Binding Cassette Subfamily G Member 2 (ABCG2)–positive migratory side population (SPm) fraction of CSCs exposed to extreme hypoxia followed by reoxygenation." (PMID 36248858, 2022). "Because ABCG2 and other drug transporter proteins are often upregulated in tumor-initiating cells, these cells are less sensitive to most conventional chemotherapeutic drugs than non-tumor-initiating cells." (PMID 35433695, 2022). "The ABCG2 biomarker that is recognized for the stemness phenotype was also significantly reduced in the tumor tissues following treatment with PUMP (OP) and PUMP (ASA + OP)." (PMID 35892853, 2022). "The relationship between ABCG2 gene expression and a total of 47 immune checkpoint genes in tumor immune responses was further analyzed." (PMID 36555598, 2022). "Expression of two key drug transporters i.e., ABCC1 and ABCG2 were analysed in tumor and adjacent normal breast tissues in local as well as TCGA cohort." (PMID 36309544, 2022). "ABCG2 substrate chemotherapeutic substances in tumor cells can be transferred to the outside of tumor cells, which reduces the sensitivity of tumor cells to chemotherapy drugs." (PMID 35897925, 2022). "We analyzed the relative expression of ABC-transporters’ genes ABCB1, ABCC1, and ABCG2, transcription factor YB-1 and MVP gene associated with the distribution of xenobiotics in cytoplasm, in 70 tumor samples." (PMID 35328603, 2022). "The non-treated primary LC samples were collected and grouped based on mutational background; then, qRT-PCR analysis was performed to detect ABCB1 and ABCG2 expression in the resected tumours." (PMID 34065402, 2021). "In summary, the reversal effect of CBZ against ABCG2-mediated TPT resistance has been confirmed in the TPT-resistant human NSCLC NCI-H460/TPT10 tumor xenograft model." (PMID 33829017, 2021). "Nevertheless, our study indicates that the ABCG2-mediated drug resistance involves 3D tumor formation with increased CSC/CIS properties." (PMID 33562088, 2021). "–7 Tumor cell lines with elevated ABCG2 activity exhibited good responses to Ko143 for the enhancement of PpIX and PDT, but not tumor cell lines with little ABCG2 activity." (PMID 34545713, 2021). "Most notably, the expression of ABCB1, commonly known as P-glycoprotein (P-gp), and ABCG2, also known as BCRP or the breast cancer resistance protein, in tumor cells has been correlated to poor patients prognosis in numerous studies." (PMID 34993424, 2021). "Taken together, these results demonstrate that ADQ suppresses autophagy-promoting tumor growth by inhibiting the GRP78/β-catenin/ABCG2 axis in vivo, thereby increasing the chemosensitivity of breast CSCs to taxol." (PMID 34149413, 2021). "Specific ABCG2 inhibitor Pantoprazole or ABC transporter inhibitor Verapamil can reduce tumor resistance to platinum." (PMID 33588867, 2021). "It has been demonstrated that promoter hypermethylation, which frequently occurs in tumor cells, leads to repressed transcription of the ABCG2 gene, lowered protein level, and consequently increased drug sensitivity." (PMID 33801813, 2021). "ABCG2 was correlated with tumor progression, prognosis and drug resistance, and ABCB10 was associated with tumor progression as well as prognosis." (PMID 33825659, 2021). "Expression of Aldehyde dehydrogenase, drug transporters like ABCG2 and various other signaling molecules are also known to mark CSCs in a given tumor." (PMID 34712602, 2021).
tumor (continued). "Nanoformulations such as irinotecan-loaded liposomes with benzoporphyrin derivative for photodynamic therapy (PDT) were able to overcome ABCG2-mediated resistance, decreasing tumor volume from 70% to 25% in mice bearing pancreatic tumors." (PMID 33923200, 2021). "Total RNA was isolated from the tumor tissues or tumor cells, and the expression of ABCG2 was analyzed by qPCR." (PMID 33509236, 2021). "Our study also suggested that the ABCG2-mediated drug resistance involves 3D tumor formation with increased CSC/CIS properties." (PMID 33562088, 2021). "Studies have found that PI3K/Akt can regulate the expression of ABCG2 in tumor cells, and estradiol has a clear role in regulating the PI3K/Akt pathway." (PMID 34144706, 2021). "Staining for ABCG2 showed membranous as well as cytoplasmic reaction both in the tumour samples and adjacent control endometrium." (PMID 33917029, 2021). "Our studies presented here show that NCX4040, a nitric oxide donor derived from aspirin, was significantly cytotoxic to both ABCB1 and ABCG2-expressing human MDR tumor cells." (PMID 33918289, 2021). "For the first time, our data demonstrate that DD is a tumor-promoting factor that affects metastasis and self-renewal by upregulating ABCG2 expression." (PMID 32742477, 2020). "EP300 KD abolished the CSC phenotype by reducing ABCG2 expression, side population cells and tumorsphere formation capacity in vitro as well as tumor formation in a xenograft mouse model in vivo." (PMID 33167919, 2020). "Immunohistochemistry (IHC) analyses were performed on the primary tumor tissue in order to classify samples as high or low presence of ABCG2 protein." (PMID 32708825, 2020). "We demonstrated that knockdown of EP300 reduced the expression of ABCG2, eliminated side population cells and decreased tumor initiating as well as metastatic potential." (PMID 33167919, 2020). "It has been reported that HSVTK suicide gene therapy was less efficient in GSC than in tumor cells because of the elimination of GCV by ABCG2-mediated efflux." (PMID 32354013, 2020). "In this regard, co‐delivery of DOX and Fidarestat has been shown to lower the MDR1, MRP1 and ABCG2 drug transporters, thereby reducing the drug efflux in tumour cells and decreasing the drug resistance." (PMID 32633024, 2020). "For all patients, a fresh tumor biopsy will be obtained prior to treatment and this biopsy will be used for ABCG2 and SRPK-1 staining." (PMID 32708825, 2020). "Among them, ABCB1 (P-gp/MDR1), ABCCs (MRPs) and ABCG2 (BCRP/MXR/ABCP) are the main members of the ABC transporters related to MDR in tumor cells." (PMID 32903706, 2020). "As previously reported, we established ABCB1- or ABCG2-overexpressing tumor xenograft models, with a slight modification." (PMID 32098067, 2020). "Penetration of the human blood–brain barrier by AZD1775 is facilitated by uptake into the CNS through the OATP1A2 transporter and limited transporter-mediated efflux by ABCB1/ABCG2 in the relatively acidic tumor microenvironment." (PMID 32204315, 2020). "We tested the independence of ABCG2/TOP1 status in multivariable models including tumor site, MSI status, mucinous histology, and BRAF and KRAS mutation status (without interaction terms)." (PMID 32326511, 2020). "One exploratory analysis study was performed and suggested that the response to irinotecan is highly related to tumor ABCG2 mRNA expression." (PMID 33692943, 2020). "Studies in peripheral tumors and with tumor cells in vitro share these results, showing an increase in 5-ALA-mediated PpIX accumulation in tumor tissue when combined with ABCG2 inhibitors." (PMID 32582530, 2020). "Even in a high Trop-2 expressing tumor (~250,000 Trop-2 molecules per cell), SG was unable to overcome ABCG2-mediated resistance in vivo." (PMID 33196706, 2020).
tumor (continued). "The overexpression of ABCG2/BCRP in a side population of MCF7-derived cells with stem cell-like features was associated with resistance to mitoxantrone (anthracycline anti-tumor agent used to treat metastatic breast cancer; substrate for ABCG2)." (PMID 32883003, 2020). "Since CC-115 is a substrate of ABCG2, its potency is affected by ABCG2 expression; thereby the inhibition of ABCG2 via small molecular inhibitors, tumor cells will be sensitive to CC-115." (PMID 32883316, 2020). "In vivo, intratumoral injection of miR-181a mimic inhibited ABCG2 expression and enhanced the anti-tumour activity of MX in a nude mouse xenograft model." (PMID 32577155, 2020). "All SCLC CTCs are CD24-positive but lack expression of CD44 and ABCG2 in contrast to the SCLC tumor lines which show a phenotype more similar to that of CSCs." (PMID 31446534, 2020). "Gemcitabine upregulated the expression level of ABCB1 and ABCG2 in the tumor section when compared with solvent (p < 0.05)." (PMID 31652737, 2019). "ABCG2/ABCB1 ratios in surgically resected tumor tissue (1.4 ± 0.2) were comparable to previously reported ABCG2/ABCB1 ratios in isolated human micro-vessels (1.3), which suggested that no overexpression of ABCB1 or ABCG2 occurred in the investigated tumors." (PMID 31832814, 2019). "DT treatment to GHR or ABCG2 knockdown xenografts significantly inhibited the tumor growth compared to control or DT alone treatment." (PMID 30617282, 2019). "The authors reported that the downregulation of ABCG2 significantly enhanced chemotherapeutic drug-induced apoptosis, leading to superior control of tumour growth." (PMID 31835751, 2019). "The subfamily ABCB1/MDR1/P-glycoprotein, ABCC1/MRP1, and ABCG2/BCRP play a major role in producing MDR in tumor cells." (PMID 31472682, 2019). "At present, researchers believe that P-gp and ABCG2 can pump most chemotherapy drugs out of the cell, resulting in a reduction in the intracellular drug concentration and showing that tumour cells possess extensive drug resistance mechanisms, namely, MDR." (PMID 31949471, 2019). "ASPP2 depletion resulted in upregulation of transcription factor Oct4, ATP-binding cassette transporter Abcg2, and Ck-19, a putative marker of tumor-initiating HCC cells, in HCC-LM3 and HepG2 cells." (PMID 31685796, 2019). "On the other hand, the expression level of ABCG2 was correlated with gender, tumor size, and tumor stage (P=0.02, 0.04, and 0.001, respectively)." (PMID 31341476, 2019). "This study showed that four epidermal growth factor receptor tyrosine kinase inhibitors (EGFR TKIs) (gefitinib, erlotinib, lapatinib, and afatinib) were transported from tumor cells as substrates of ABCG2." (PMID 31340525, 2019). "Resistance genes and proteins are an important reason for the occurrence of drug resistance in tumour cells, and P-gp and ABCG2 are the most common proteins in this regard." (PMID 31949471, 2019). "To confirm the role of GHR and ABCG2 knockdown on tumor growth, we performed IHC and immunoblot analyses on the xenograft tumors for key markers involved in cell proliferation, apoptosis, and EMT." (PMID 30617282, 2019). "ABCG2 played an important role in protecting tumor cells from cytotoxic damage of antineoplastic drugs." (PMID 30687102, 2018). "ABC transporters, such as multidrug resistant protein 1 (MDR1) or ABCG2, are known effectors of chemoresistance across multiple tumor types." (PMID 29373514, 2018). "To get more specific ABCG2-positive tumor-initiating cells from LC patients, we sorted CD45−/CD326+/CD338+ cells from 10.0 ml of blood cells from LC patients; then we injected the cells into the tail vein of Balb/C nu/nu mice for 4 months." (PMID 29706625, 2018). "The expression of PRMT3 and ABCG2 and their association were investigated in PDAC tumor tissues (N = 81) by immunohistochemical staining." (PMID 30577570, 2018). "Overexpression of certain ABC transporters such as ABCG2/BCRP and ABCB1/Pgp in tumor cells is linked with resistance to chemotherapy." (PMID 29713280, 2018).
tumor (continued). "We found that the tumor cells of HCC patients have significantly higher ABCG2 than the adjacent normal liver tissues, while the cells of sorafenib-resistant HCC patients expressed the highest ABCG2." (PMID 29844385, 2018). "ABCG2 cytoplasmic expression was found in 56% of the patients, with most positive tumor samples showing a membranous staining and some diffuse cytoplasmic staining." (PMID 28880238, 2017). "There was lower expression of the multi-drug resistant transporter, ABCG2 gene, in those tumours with a pCR following NAC." (PMID 28697743, 2017). "Immunohistochemistry staining was performed to grade the expression of ABCG2 as ABCG2(−): less than 10% of tumor cells stained; ABCG2(+): weak membrane staining; and ABCG2(++): moderate or strong membrane staining." (PMID 28347288, 2017). "We recently published a paper on the analytical validation of anti-ABCG2 antibodies for immunohistochemistry (IHC) on formalin-fixed paraffin-embedded tumor tissue." (PMID 28880238, 2017). "Divided as high ABCG2 expression group and low ABCG2 expression group, tumor samples contribute to the dominant portion of high ABCG2 expression group, while in low ABCG2 expression group, non-cancerous tissues contribute to the dominant portion." (PMID 28029654, 2017). "There are significant differences of mRNA levels of ABCG2 between normal kidney tissue and tumor (p = <0.0001), and at various stages (p = 0.024)." (PMID 28347288, 2017). "EGFR activation enhanced the level of plasma membrane BCRP in head and neck squamous cancer cells, and accordantly, treatment with EGFR inhibitor erlotinib reversed tumor resistance to topotecan by reducing the expression of BCRP/ABCG2." (PMID 29291022, 2017). "Although the best-known role for ABCG2 is the ability to protect tumor cells from death by effluxing anticancer drugs from target cells." (PMID 28059154, 2017). "The results showed that higher ABCG2 expression presents a significant inclination related to larger tumor size, deeper local invasion and tendency of lymph node metastasis." (PMID 28029654, 2017). "Some studies reported that reduced expression of CREB suppressed the expression of ABCG2, which plays critical roles in conferring multidrug resistance in tumor cells." (PMID 27926502, 2017). "High expression levels of ABC transporters, especially ABCG2, in normal stem cells and tumor stem cells are considered to be responsible for drug resistance." (PMID 28219421, 2017). "This suggested that ABCG2 overxpression decreased the anti-tumor activity of DMC on GSCs xenograft tumors." (PMID 28591733, 2017). "Meanwhile, in vivo, ABCG2 was found decreased in mice tumor tissues in the presence of US-MB compared with the other group." (PMID 28935760, 2017). "The study showed a significant decrease in the expression of ABCG2 mRNA in the primary tumor tissue (about 100-fold compared with normal tissue), and about a five-fold increase in ABCG2 mRNA expression in the metastases from irinotecan-treated patients." (PMID 28880238, 2017). "When GSCs transfected with ABCG2 shRNA or overexpressing ABCG2 were xenografted and the tumor-bearing, immunodeficient mice were treated with DMC, ABCG2 expression suppressed the tumor proliferation rate (T/C %)." (PMID 28591733, 2017). "Since drug-resistance related proteins, P-gp, MDR-1 and ABCG2 have been known to promote tumor cell growth and drug resistance." (PMID 29137307, 2017). "Herein, the high expression characteristic of ABCG2 in GC cells is consistent with the observation through IHC of tumor tissues." (PMID 28029654, 2017). "ATP-binding cassette sub-family G member 2 (ABCG2) is a xenobiotic transporter that confers resistance to a variety of anticancer drugs by transporting intracellular drugs out of tumor cells." (PMID 28591733, 2017). "Patients with high expression of either ABCG2 or CRKL in tumor tissue presented a significant tendency towards poor prognosis and high mortality (P < 0.05)." (PMID 28029654, 2017).